INS (insulin)
Diseases named in the same sentence as INS in open-access papers (continued):
Sharing a sentence is not in itself a finding about the gene and the disease.
type 2 diabetes (continued). "This provides insights into LEAP2 being used as a therapeutic agent for insulin secretion in type 2 diabetes and obesity as LEAP2 most likely directly increases insulin production rather than insulin sensitivity." (PMID 39796232, 2025). "In patients with type 2 diabetes, both GLUT4 membrane translocation and expression are reduced in skeletal muscle, and exercise enhances GLUT4 translocation regardless of insulin sensitivity." (PMID 40441535, 2025). "A detailed characterization of daily glycemic levels and insulin use over the course of hospitalization and across different hospital shifts has not been explored in nonintensive care unit (non-ICU) patients with type 2 diabetes monitored by either POC or CGM." (PMID 40980547, 2025). "Unlike typical type 2 diabetes, DM1 patients often exhibit a unique insulin secretion pattern during the early stages of impaired glucose tolerance." (PMID 41018201, 2025). "To rule out the possibility that the lower insulin secretion in the older participants was simply due to the high prevalence of IGT and type 2 diabetes, we examined the effects of aging in people with NGT." (PMID 40002793, 2025). "In both the T2D-B and T2D-MDI treatment cohorts, isCGM users with suboptimal glycaemic management and baseline HbA1c ≥58.5 mmol/mol (≥7.5%) were compared with HbA1c-matched BGM control participants with type 2 diabetes on basal insulin and multiple daily injection regimens." (PMID 39460755, 2025). "Moreover, insulin’s anabolic properties, caloric intake adjustments to prevent hypoglycemia, and reduced glycosuria after surgery may all explain why patients with diabetes often lose less weight compared to subjects not affected by type 2 diabetes." (PMID 41515225, 2025). "Note: in this animal model of poorly controlled type 2 diabetes, the VLCD markedly improved hepatic, but not peripheral, insulin sensitivity." (PMID 41009753, 2025). "Additionally, the evolution of Type 2 diabetes definitions over time, particularly the ADA’s 2009 inclusion of the HbA1c test for diagnosis, could have led to the inclusion of diabetic individuals in pre-2009 cycles, potentially overestimating insulin levels in pre-2009 cycles." (PMID 39606490, 2024). "From 1 January 2010 to 21 December 2023, 176,409 individuals with type 2 diabetes receiving SGLT2i plus insulin, 207,034 receiving GLP1-ra plus insulin and 1,922,312 individuals receiving insulin but no SGLT1i/GLP1-ra were identified." (PMID 38584180, 2024). "Misdiagnosis of type 1 diabetes as type 2 diabetes in adolescents and adults can lead to DKA, as this misdiagnosis means that these individuals are often not started on insulin." (PMID 38910151, 2024). "Most of them had type 2 diabetes (T2DM) without insulin (48.63%), followed by those with T2DM on insulin (36.26%), and patients with type 1 diabetes (T1DM) (15.11%)." (PMID 39273732, 2024). "On the other hand, Type 2 diabetes, formerly referred to as non-insulin dependent or adult-onset diabetes mellitus (NIDDM), occurs due to the body’s inability to effectively use insulin." (PMID 38053195, 2023). "Men with NAFLD were more obese and more centrally obese, had higher concentrations of ALT, LDLC, TAG, glucose, insulin, hs-CRP, and FFAs, and more often had type 2 diabetes than men without NAFLD." (PMID 36837886, 2023). "Thus Laron syndrome, an experiment of nature, showed that in humans, low(er) activity of the insulin/IGF-I signaling pathway and high insulin sensitivity may play a crucial role in the protection from diseases typically related to Western civilization, such as type 2 diabetes and cancer." (PMID 36901984, 2023). "In type 2 diabetes, GIP has a limited ability to stimulate insulin secretion during hyperglycaemia and does not significantly reduce plasma glucose concentrations." (PMID 37430117, 2023). "In people without type 2 diabetes, exendin 9-39 — presumably through GLP1R blockade — decreases insulin secretion in response to glucagon." (PMID 37751301, 2023).
type 2 diabetes (continued). "GLP-1 receptor agonists have been used successfully and safely in type 2 diabetes mellitus (T2DM) and do not induce insulin desensitization after prolonged use, as they do not activate insulin receptors in normoglycemic subjects and thus do not cause hypoglycemia." (PMID 36258018, 2023). "Furthermore, upregulation of lipid and glycogen synthesis in insulin target tissues, such as adipose and liver, in response to the “direct” transfer of GPI-APs may be interpreted as a mechanism to override peripheral insulin resistance in type II diabetic patients to a certain (limited) degree." (PMID 36902257, 2023). "We observed no statistical differences for fasting insulin (HNF1A‐MODY studies: SMD 0.18 [95% CI −0.21, 0.58] mIU/l, p = .36, n = 6; I2 = 66%, Ph = .01; type 2 diabetes studies: SMD −0.60 [95% CI −1.24, 0.04] mIU/l, p = .07, n = 3; I2 = 77%, Ph = .01)." (PMID 37226652, 2023). "Prolonged increase of plasma nonesterified fatty acid (NEFA) levels reduces insulin-stimulated glucose utilization in peripheral tissues, and atypically high levels of NEFA are thought to play an essential role in the development of type 2 diabetes." (PMID 37451484, 2023). "The insulin (INS) gene was only expressed in pancreatic β-cells, and the glucagon (GCG) gene was only expressed in pancreatic α-cells in both nondiabetic and type 2 diabetes donors." (PMID 37147373, 2023). "This suggests that, in type 2 diabetes, β cells do not have increased dependency on glucagon signaling via the GLP1R to maintain insulin secretion." (PMID 37751301, 2023). "How were these devised and what are the impacts (both positive and negative) of such insulin analogs against TIDM (type-I diabetes mellitus) and TIIDM (type-II diabetes mellitus)?" (PMID 35723344, 2022). "Other studies have described a reduction of glycated hemoglobin and also negative correlation with insulin and HOMA-IR, and positive with QUICKI index, after supplementation of 100 to 200 mg/day of ubiquinone to patients with type 2 diabetes." (PMID 36009259, 2022). "Norwegian guidelines from 2009 recommend that persons with type 2 diabetes in need of GLD, should start treatment with Metformin, and if not reaching treatment goals, should add insulin or another non-insulin GLD." (PMID 35701772, 2022). "Despite the lack of changes in hepatic glycogen and insulin sensitivity, we did find that our 10 h TRE protocol decreased 24 h glucose levels in individuals with type 2 diabetes, primarily driven by decreased nocturnal glucose levels." (PMID 35871650, 2022). "This negative correlation between fasting ghrelin and insulin has also been reported in previous studies, and our data are in line with these results and this negative correlation could eventually lead to type 2 diabetes and cardiovascular disease in obese individuals." (PMID 36355134, 2022). "Similar to the study in type 2 diabetes, adults with impaired glucose tolerance (IGT), randomized to dietary advice to follow a low GI diet, had no change in insulin sensitivity, but an improvement in the disposition index." (PMID 35215537, 2022). "In addition, multiple studies have shown that at least 10% of Type 2 diabetes (T2D) patients are IAbs positive and a correct diagnosis in clinic is challenging, as the clinical phenotype does not initially require insulin for treatment." (PMID 36992730, 2022). "In patients with type 2 diabetes (T2DM), GLP-1 infusion significantly improved endothelial function, irrespective of changes in insulin sensitivity." (PMID 35945358, 2022). "To our surprise, despite a wealth of evidence suggesting that insulin sensitivity can be improved in older adults via HIIT, and that HIIT can combat the severity of type 2 diabetes, we were not able to show improvement in any marker of insulin sensitivity." (PMID 35761262, 2022).
type 2 diabetes (continued). "We hypothesized that repeated oscillations increases insulin secretion and sensitivity, and improve metabolic health in patients with obesity with or without type 2 diabetes (T2DM)." (PMID 36531168, 2022). "In type 2 diabetes (T2DM), chronic hyperglycemia that does not reduce due to insulin insensibility in other tissues results in hyperinsulinemia, which causes failure not just of the β-cell, but also other organ damage and chronic inflammation." (PMID 35399507, 2022). "However, type 2 diabetes (T2D) usually occurs first in adults whenever the body becomes insulin resistant or fails to deliver enough insulin." (PMID 35889889, 2022). "Currently, when glycosylated hemoglobin (HbA1c) is not well controlled, add‐on therapy with insulin is the next step for patients with type 2 diabetes (T2DM) who fail glycemic control with lifestyle intervention and non‐insulin agents, as recommended by most of the treatment guidelines." (PMID 35023626, 2022). "SGLT2 inhibitors are a new class of agents used to treat type 2 diabetes mellitus (T2DM); they reduce glucose reabsorption and thereby reduce blood glucose without stimulating insulin release." (PMID 35215315, 2022). "We and others have previously reported increases in insulin-stimulated GDR by ~10-20% in obese individuals with and without type 2 diabetes in response to 8-10 weeks supervised endurance training on cycle ergometers or treadmill." (PMID 36387850, 2022). "Type 2 diabetes mellitus (T2DM), diagnosed when the pancreas could no longer produce sufficient insulin, accounts for 90-95% of all diabetic cases." (PMID 34777252, 2021). "Hence, long-term management of diabetes type 2 with regular insulin therapy may not be beneficial." (PMID 33708999, 2021). "Type II diabetes mellitus (T2DM) is a serious, chronic disease that occurs either when the pancreas does not produce enough insulin (a hormone that regulates blood glucose), or when the body cannot effectively use the insulin it produces." (PMID 34682532, 2021). "Type 2 diabetes mellitus (T2DM) is a long-term chronic nutritional metabolic disorder disease that is characterized by high blood sugar, relative lack of insulin, and insulin resistance." (PMID 34621771, 2021). "Moreover, our saccharide preload may also have positive consequences on glucose metabolism in patients with type 2 diabetes since blood glucose and insulin levels did not raise above fasting values after preload application but still exert its appetite suppressing effect." (PMID 33891230, 2021). "Although a different type of insulin stimulus, in vivo insulin does not change p38 MAPK phosphorylation in adults with type 2 diabetes." (PMID 34943997, 2021). "As we demonstrated in preclinical models, insulin and IGF-1 stimulated eNOS phosphorylation were blunted in SVEC from patients experiencing type 2 diabetes, compared with patients without type 2 diabetes." (PMID 34420367, 2021). "Type 2 diabetes mellitus (T2DM) is characterized by hyperglycemia, insulin resistance, and relative lack of insulin secretion." (PMID 34136485, 2021). "We recently documented that IQGAP1 is necessary for optimal activation of insulin signaling, and mice lacking IQGAP1 have impaired glucose tolerance, which is a fundamental component of type 2 diabetes." (PMID 33191271, 2021). "Type 2 diabetes mellitus (T2DM), a metabolic disorder characterized by high blood glucose, insulin resistance and a relative lack of insulin, is considered a global epidemic, with the number of patients estimated at about 422 million and constantly on the rise." (PMID 35010914, 2021). "On the other hand, Pegbelfermin as an agent for type-2 diabetes mellitus (T2DM) showed no change in body weight or glycated hemoglobin, but improved insulin sensitivity, triglycerides, and high-density lipoprotein cholesterol levels." (PMID 34572066, 2021). "Insulin and IGF-1 stimulated Akt phosphorylation were similar when comparing SVEC from patients with and without type 2 diabetes." (PMID 34420367, 2021).
type 2 diabetes (continued). "Such individuals were older, with higher BMI, serum glucose, insulin, alanine aminotransferase (ALT) and triglyceride (TG) concentrations than those who did not develop prediabetes or type 2 diabetes (n = 1454)." (PMID 34309471, 2021). "Type 2 diabetes (DM2) is characterized by insulin resistance and abnormal insulin secretion leading to relative rather than absolute insulin deficiency." (PMID 33100218, 2020). "In 1986 it was demonstrated that the incretin effect is severely reduced or even absent in patients with type 2 diabetes (T2DM), even in patients with a considerable insulin secretory capacity." (PMID 33339298, 2020). "We found statistically significant positive correlations between vaspin plasma concentration and HOMA-IR, fasting insulin and HOMA-B, as well as a negative correlation between plasma vaspin level and HOMA-S in untreated obese patients with type 2 diabetes." (PMID 32917052, 2020). "Type 2 diabetes (T2DM) is a potentially reversible disease, characterized by high blood glucose, insulin resistance and relative lack of insulin." (PMID 33374507, 2020). "Type 2 diabetes mellitus (T2DM), characterized by high blood sugar in the context of insulin resistance (IR) and a relative lack of insulin, is a long-term, non-communicable, multisystem disease that has reached epidemic proportions." (PMID 33114258, 2020). "Here, this study evaluated the same parameters, including HbA1c and lipid profiles, for up to 60 weeks for patients with type 2 diabetes receiving RCEG treatment, with or without OHA/insulin therapy." (PMID 33568997, 2020). "However, not all individuals with type-2 diabetes develop beta-cell dysfunction/mass and insulin production; some individuals with type-2 diabetes may have higher than normal fasting insulin (despite this increased fasting insulin not matching physiologic needs)." (PMID 32153503, 2020). "Dapagliflozin significantly reduced the HbA1c level and FBG of type 2 diabetes patients as add-on therapy, regardless of the type of the coadministered OHA or insulin within a 6-month treatment period." (PMID 31053747, 2019). "Type II diabetes mellitus (T2DM), a type of metabolic disorder, is characterized by dyslipidemia in respect to insulin resistance and relative lack of insulin." (PMID 31189741, 2019). "However, type 2 diabetes is expected to develop in 20–50% of these women within 10–20 years, and the GDM offspring shows a two- to eightfold increased risk of obesity, metabolic syndrome, type 2 diabetes, and impaired insulin secretion and sensitivity than offspring of women without GDM." (PMID 30717458, 2019). "In human islets from non-diabetic donors and donors with type 2 diabetes, acute exposure to GIP has been reported to be superior to acute exposure with equimolar amounts of GLP-1 in terms of insulin release." (PMID 31443356, 2019). "Type 2 diabetes mellitus (T2DM) is a common metabolic disorder characterized by high blood sugar, insulin resistance, and a relative lack of insulin." (PMID 31417393, 2019). "Consequently, the induction of MMP‐2 by insulin may contribute to the degradation of ECM, the breakdown of the basement membrane, increased local infiltration and distant metastasis, which may explain the increased incidence of pancreatic cancer in patients with hyperinsulinemia and type 2 diabetes." (PMID 30838710, 2019). "Type 2 diabetes (noninsulin-dependent diabetes mellitus, NIDDM) is mostly characterized by pancreatic β-cell dysfunction and decreased insulin sensitivity." (PMID 31839788, 2019). "Furthermore, a practical question is whether insulin secretagogues such as sulfonylureas, rather than insulin sensitizers such as metformin or thiazolidinediones, should be used as first-line antidiabetes medication in non-obese patients with type 2 diabetes." (PMID 29536426, 2018).
type 2 diabetes (continued). "Type 1 diabetes is caused by decreased insulin production in the pancreas whereas type 2 diabetes may develop due to obesity and lack of exercise; it begins with insulin resistance whereby cells fail to respond properly to insulin and it may also progress to decreased insulin levels." (PMID 30054579, 2018). "Arora found a negative correlation between some sphingomyelin species and insulin levels 4 days after RYGB in 16 insulin-resistant subjects, where 14 had type 2 diabetes." (PMID 29922223, 2018). "Type 2 diabetes mellitus (T2DM) is a metabolic disease that presents with symptoms of insulin resistance and lack of insulin." (PMID 30400886, 2018). "At follow-up, the very good metabolic control on a low insulin dose and negative IA2 antibodies led to a suspicion of glucokinase (GCK)-related maturity-onset diabetes of the young (MODY 2)." (PMID 28387648, 2017). "Low-grade inflammation is involved in the development of type 2 diabetes and cardiovascular disease (CVD); however, prospective studies evaluating inflammatory markers as predictors of changes in insulin secretion and insulin sensitivity are lacking." (PMID 28911155, 2017). "We aimed to investigate gut hormones, lipids, and insulin regulation in response to a meal test in HNF1α defect carriers (MODY3) compared to non-diabetic subjects (controls) and type 2 diabetes (T2D)." (PMID 28493909, 2017). "Type 2 diabetes mellitus (T2DM) is one of the most common noncommunicable diseases characterized by insulin resistance and impaired insulin secretion." (PMID 27777959, 2016). "GADAb is also detected in adult-onset patients initially diagnosed as having type 2 diabetes (T2D) who do not require insulin treatment but may become insulin-dependent within a few years after diagnosis." (PMID 27177031, 2016). "Type 2 diabetes mellitus (T2DM) is characterized by insulin resistance, with or without defects in insulin production and secretion." (PMID 27374075, 2016). "In pancreatic islets of human type-2 diabetes, Syn-1A levels are severely reduced which may presumably affect β-cell L-type Cav function that may contribute to the reduced efficiency of exocytosis of predocked insulin SGs, with ensuing reduction to absent first phase GSIS." (PMID 26848587, 2016). "Exposure categories (insulin use-no insulin use and insulin use-NIAD only use) are hard to define and compare, because many patients with type 2 diabetes are using insulin (analogues) simultaneous with NIADs." (PMID 26242987, 2015). "Similar increases in VLDL production have been observed in obese, non-diabetic, insulin-resistant individuals, suggesting a critical role of insulin resistance in the pathophysiology of VLDL overproduction in type 2 diabetes." (PMID 25725623, 2015). "Type 2 diabetes mellitus (T2DM) is a metabolic disorder that is characterized by hyperglycemia resulting from insulin resistance and relative lack of insulin." (PMID 25352807, 2014). "In our study, no family history of type 1 or type 2 diabetes was found in SGA children, so the lower glucose stimulated insulin secretion can be a consequence of intra uterine growth restriction and of consecutively impaired β-cell function." (PMID 24979613, 2014). "Another finding with regard to clinical application is the fact that insulin–resistant, but not –sensitive, acromegalic patients showed elevated EGP, which is in general seen only following type-2 diabetes manifestation." (PMID 25517727, 2014). "Insulin sensitizing agents significantly decreased both PWV and IMT of the carotid artery of type 2 diabetes patients, irrespective of their glucose-lowering effects." (PMID 23671853, 2013). "Similar to the metabolic phenotype in Id2−/− mice, enhanced insulin sensitivity and increased glucose uptake by WAT and BAT were observed in a non-obese type 2 diabetic mice model in response to β3-adrenergic receptor activation." (PMID 24023810, 2013).